RAG1 (recombination activating 1)
Diseases named in the same sentence as RAG1 in open-access papers (continued):
Sharing a sentence is not in itself a finding about the gene and the disease.
Autoimmunity (23 papers, 2011 to 2026). The occurrence of an immune reaction against the organism's own cells or tissues. "In certain diseases, such as delayed onset combined immunodeficiency with granulomas and/or autoimmunity due to RAG1 mutation, common variable immunodificiency, and etc, AIGAs could be detected." (PMID 40083428, 2025). "Hence recipient sub-lethally irradiated Rag1-deficient mice administered scurfy bone marrow were unable to maintain Treg function, lost weight and died within 50 days; in contrast, co-administered wildtype bone marrow cells prevented autoimmunity completely." (PMID 40949964, 2025). "Prediabetic and diabetic NOD mice transferred autoimmunity to 100% of NOD Rag1-KO recipients (n = 6 of 6), with diabetes developing between 50 and 75 or 25 and 40 days after transfer, respectively." (PMID 41252212, 2026). "Conditioned prediabetic NOD controls also transferred autoimmunity to 100% of NOD Rag1-KO recipients followed long-term (n = 4 of 4), with diabetes developing 60–80 days after transfer." (PMID 41252212, 2026). "Hypomorphic RAG1 or RAG2 mutations cause primary immunodeficiencies and can lead to autoimmunity, but the underlying mechanisms are elusive." (PMID 34622798, 2021). "The most often used animal models are the Rag1 and Rag2 knockout (KO) mice and rats, which are characterized by the absence or abnormality of B and T lymphocyte development, autoimmunity, and inability to mount adequate adaptive immunity to infections." (PMID 29734775, 2018). "Depending on the types of genetic mutations in the RAG1 or RAG2 genes, autoimmunity associated with expansion of oligoclonal T cells and production of autoantibodies is also often observed in affected patients." (PMID 29734775, 2018). "Both FOXP3 and RORγt were undetectable in three patients with IL2RG, RAG1 and STAT1 mutations, implying that Treg and Th17 cells were almost completely absent, and therefore they had increased risks of developing autoimmune disorders and opportunistic infections." (PMID 32670274, 2020). "To conclude, we have not observed any signs of apparent autoimmunity or inflammation, either from ex Treg subsets or from the non-Treg cells, in vivo and in vitro, in tumor bearing mice or in RAG1-/- mice." (PMID 39234236, 2024). "To further evaluate risks of autoimmunity and inflammation, we evaluated the rate of divisions of conventional CD4+ T cells and RAG1-/- cells in vivo, and found no increase in ASO FOXP3 treated group." (PMID 39234236, 2024).
melanoma (23 papers, 2013 to 2025). A malignant, usually aggressive tumor composed of atypical, neoplastic melanocytes. "The melanoma cell line B16-F10 was subcutaneously inoculated on the back of the Rag1 knock-out mice, which are deficient in T and B cells." (PMID 36497152, 2022). "In contrast, Rag-deficient (Rag1−/−) and Rag1−/−;Cd300a−/− mice showed comparable levels of tumor development and survival after injection of B16 melanoma cells." (PMID 34751648, 2021). "Indeed, underscoring their poor immunogenicity, BrafV600E melanoma cells formed progressively growing tumors upon implantation into wild-type (WT) mice, and this was only marginally enhanced in T- and B-cell-deficient Rag1−/− mice." (PMID 26343581, 2015). "From each treated mouse, we adoptively transferred harvested cells into a Rag1–/– mouse implanted with B16 melanoma tumor." (PMID 40569687, 2025). "To do so, we intradermally injected 1 × 106 wild-type or JMJD1B knockout B16F10 melanoma cells into RAG1 KO mice, and the tumor growth was evaluated in the subsequent days." (PMID 39409021, 2024). "We then adoptively transferred these engineered T cells into Rag1–/– recipient mice by intravenous injection, and then subcutaneously injected B16 melanoma cells into the same mice." (PMID 36241625, 2022). "As Th9 cells have been well documented to suppress tumor growth, we firstly utilized an experimental mouse model of melanoma in which Rag1−/− mice were injected with B16F10 melanoma cells and treated with adoptive transfer of Th9 cells." (PMID 36241625, 2022). "Adoptive transfer of Lsp1 KO T cells to Rag1 KO mice was more effective in repressing melanoma growth than transfer of Lsp1 Tg T cells." (PMID 33020243, 2020). "Adoptive transfer of Lsp1 KO T cells to Rag1 KO mice was more effective in suppressing melanoma growth than transfer of Lsp1 Tg T cells." (PMID 33020243, 2020). "Adoptive transfer of Lsp1 KO or Lsp1 Tg T cells was performed in B16 melanoma-challenged Rag1 KO mice." (PMID 33020243, 2020). "To address this question, we first generated subcutaneous B16-ova melanoma in RAG1−/− mice and i.t. treated them with the same dose of SLR14 or vehicle as for YMR1.7." (PMID 31601678, 2019). "However, administering recombinant IL-9 (rIL-9) to tumor-bearing wild-type and Rag1(−/−) mice inhibited the growth of both melanoma and lung carcinoma." (PMID 41148223, 2025). "To validate whether INHBA-induced tumor growth is mediated by the inhibition of adaptive antitumor immunity across multiple melanoma models, we transplanted tumor cells into immunodeficient Rag1-/- mice." (PMID 35580932, 2022). "Lsp1-deficient T cells more strongly repressed tumor progression in Rag1 KO mice challenged with B16 melanoma as compared with Lsp1-overexpressing T cells and vehicle alone (without mature T cells), which confirms that loss of Lsp1 in T cells specifically mediates the antitumor effect." (PMID 33020243, 2020). "To determine the role of the innate and adaptive component of the immune system in Zn-mediated tumor progression, we used RAG1−/− and C57BL/6 WT mice, in which B16F10 melanoma cells were implanted." (PMID 39247196, 2024). "To test this notion, we inoculated subcutaneously the wild-type and mutant B16 melanoma cells deleted for Mll3, Mll4, or both (DKO) into immune-competent syngeneic C57BL/6J mice or immune-compromised BALB/c nude mice and Rag1−/− mice." (PMID 36323669, 2022). "We also reported a significant increase of the expression of RAG1 and RAG2, genes known to be involved in B cell and T cell receptor rearrangements, in melanoma compared to normal skin, consistent with our findings of secondary lambda rearrangement and VH replacement." (PMID 37291228, 2023). "To functionally determine whether T cells are involved in the anti-metastatic effect of metformin, we injected B16F10 melanoma cells into C57BL/6 (WT), RAG1−/−, CD8−/−, and CD4−/− mice." (PMID 29899823, 2018).
melanoma (continued). "This was confirmed in our experimental setting: IL15-only expressing virus, consistent with published data, showed therapeutic effect against murine melanoma tumors in the RAG1-knockout background indistinguishable from vMyx-tdTr." (PMID 25329832, 2014). "We compared WT (wildtype) with Rag1–/–, Batf3–/–, Clec9agfp/gfp, sGsn–/– or sGsn–/– Clec9agfp/gfp mice implanted with transplantable tumor cell lines, including MCA-205 fibrosarcoma, 5555 BrafV600E melanoma and B16-F10 LifeAct (LA)-ovalbumin (OVA)-mCherry melanoma." (PMID 36162919, 2022). "Here we show that relapse rates of subcutaneous B16 melanoma tumours treated topically with ingenol mebutate were not significantly different in C57BL/6 and Rag1-/- mice, suggesting B and T cells do not play a major role in the anti-cancer efficacy of ingenol mebutate." (PMID 27100888, 2016).
lymphopenia (19 papers, 2012 to 2025). Reduction in the number of lymphocytes. "In this model, naïve CD4 effector T cells (CD4+CD25-CD45RBhi) adoptively transferred into Rag1-deficient mice undergo lymphopenia-induced expansion and cause intestinal inflammation that recapitulates human IBD." (PMID 25781948, 2015). "Finally, the observation that mice carrying hypomorphic Rag1 mutations are lymphopenic and display obvious signs of T cell exhaustion further supports the notion that lymphopenia may represent an important mechanism leading to T cell exhaustion." (PMID 40804163, 2025). "As Rag1−/− mice were T/B cell deficient and might drive extensive homeostatic proliferation of naive T cells due to lymphopenia, we therefore adoptively transferred CD45.2+Tsc1 KO or CD45.2+WT naïve CD8+T cells into 4Gy-irriadiated immunocompetent CD45.1+syngeneic C57BL/6 recipients." (PMID 22363451, 2012). "SERCA proteins modulate intracellular Ca2+ levels to regulate RAG1 and RAG2 gene expression and V(D)J recombination and defects in SERCA functions cause lymphopenia." (PMID 39943104, 2025). "Four different cohorts of male mice were examined, investigating the effects of neutropenia (anti-Ly6G antibody mediated neutrophil depletion; C57BL/6), lymphopenia (RAG1 deficiency, RAG1−/−), and their combination with candesartan-mediated AT1 inhibition." (PMID 37150755, 2023). "The present study indicates that the reduction of immune cells in both the innate and adaptive immune system, specifically neutropenia (ND), and lymphopenia (RAG1−/−), independently leads to decreased brain damage after TBI." (PMID 37150755, 2023). "Despite the marked lymphopenia, our experiments revealed a comparable and functionally equivalent NK cell population in Rag1−/− compared to WT mice." (PMID 34105078, 2022). "Disseminated warts have also been frequently found in several autosomal recessive genetic defects that present with CD4 lymphopenia (e.g., RAG1, RHOH, MST1, CORO1A, DOCK8)." (PMID 31781092, 2019). "To examine the effects of lymphopenia in TBI, we employed RAG1 deficient mice." (PMID 37150755, 2023). "RAG1−/− mice appeared to be leukopenic, and lymphopenia was compensated by elevated neutrophils." (PMID 37150755, 2023). "In addition, anti-IL-18, Il18r1 KO, Foxp3DTR, and Rag1 KO mice were also analyzed to investigate the effect of IL-18 signaling, regulatory T-cell (Treg) depletion, and permanent lymphopenia." (PMID 34493727, 2021). "CD27+Ly6C− and CD27+Ly6C+ γδ T cells were sorted separately from naive mice and immediately injected into NOD;Rag1−/−;Il2rg−/− (NRG-SGM3) mice to investigate lymphopenia-driven expansion." (PMID 38816652, 2024). "Indeed, RAG1 R972Q and R972W mutant mice had similar levels of CD4+ and CD8+ T cell lymphopenia in spleen, compared to STING GOF mice (Fig. EV7A)." (PMID 40804163, 2025). "This difference does not depend on the severity of the lymphopenia, since the latter was even more profound, especially in the RAG1 R972W mutant." (PMID 40804163, 2025). "To rule out that lymphopenia in RAG1−/− drives the observed CD40L-dependent cancer cell rejection by CD8+ T cells, we investigated the rejection of TAg+ cancer cells by CD40L+CD8+ T cells in a nonlymphopenic model." (PMID 40397730, 2025). "We did not see any differences in LIP between Vα3.2+ and non-Vα3.2+ CD8+ T cells injected into Rag1–/– hosts, possibly because proliferation in Rag1–/– mice is in response to the gut microbiome rather than the lymphopenia itself." (PMID 33897691, 2021). "First, in order to exclude extrinsic influences of other hematopoietic populations and in particular Treg on lymphopenia-induced expansion, we used TCR transgenic OT-1 Rag-1 KO CD8 T cells, and adoptively transferred these cells into Rag-1 KO lymphopenic hosts." (PMID 32047502, 2020).
viral infection (16 papers, 2010 to 2024). "We further used Rag1 KO mice that were adoptively transferred with ADAP KO T cells to demonstrate that ADAP deficient T cells play a direct role in protection against virus infection." (PMID 25909459, 2015). "Further assays in mutant zebrafish of recombinant activation gene 1 (rag1) showed that all crps (except for crp2, downregulated) were already constitutively highly expressed in skin from rag1 knockouts and only increased moderately after viral infection." (PMID 33498981, 2021). "Viral infection of Rag1−/− mice induces production of vsiRNA-RISC active to direct specific RNA slicing by Ago2." (PMID 32753500, 2020). "Here, we described permanent changes in the expression of immune genes in rag1−/− zebra fish, which resemble gene expression profile changes in zebra fish that survive lethal viral infections." (PMID 28243233, 2017). "In addition to NU/J heterozygous (Foxn1nu/+) mice, a second mouse strain, recombination-activating genes 1 (Rag1) knockout mice, was included in the current study as the positive control for viral infection (27, 38, –, 40)." (PMID 39012151, 2024). "For the RAG1 site, a total of 188 off-targets were identified for SpRY and 109 of these off-targets lie in the genes involved in different molecular pathways including viral infection and cancers." (PMID 34133740, 2021). "Furthermore, the GO enrichment analysis of the genes surrounding lncRNAs that were induced after viral infection in both WT and rag1+/− showed high representation of terms related to RNA processing and metabolism." (PMID 31578442, 2019). "Myd88 −/− mice showed an enhanced susceptibility to rMA15 virus infection in C57/B6 mice and RAG1−/− mice showed no increased morbidity and mortality from rMA15 virus infection, viral replication in the lungs was detectable through 28 days post-infection." (PMID 20386712, 2010). "To test the function of the adaptive immune system in a setting where all virally infected cells are Ifnar1-sufficient, we utilized a previously published Rag1-/- splenocyte transfer in which CD4 T cells and CD8 T cells contribute to clearance of viral infection." (PMID 27327515, 2016). "To establish whether the effect of type I IFN on CD8+ T cell functional development was cell-intrinsic in the context of viral infection, we adoptively transferred naïve purified IFNAR-/- (CD45.2) or B6.SJL (CD45.1) CD8+ T cells into RAG1-/- recipient mice." (PMID 22144897, 2011). "Indeed, the observation that F11 delays but does not prevent mortality in the NSG, NOD‐SCID, and RAG1‐KO strains demonstrates that the host adaptive immune response plays an essential role in control of viral infection and prevention of death." (PMID 37767784, 2023).
Chronic colitis (15 papers, 2009 to 2025). A chronic inflammatory disease of the large intestine (colon, cecum and rectum). "Both the transfer of hTNF-KI naive T cells into Rag1−/− recipients and of WT naive T cells into Rag1−/− and hTNF-KI×Rag1−/− mice induced chronic colitis." (PMID 35383266, 2022). "Adoptive transfer of cLP Tregs treated by rTsPmy into Rag1 KO chronic colitis was utilized to verify Tregs suppressive function." (PMID 34336843, 2021). "In this model, chronic colitis develops ∼6 weeks after transfer of T cells into Rag1−/− mice and is accompanied by increased granulopoiesis." (PMID 26200014, 2015). "Chronic colitis was induced by dextran-sulphate-sodium (DSS) or transfer of CD4+CD62L+ cells into RAG1−/−-mice." (PMID 19787068, 2009). "To investigate this, we utilized a chronic colitis CD4+ T cell transfer model in Rag1−/− mice." (PMID 40887825, 2025). "Although w and others have shown that adoptive transfer of naïve syngeneic CD4+ T cells into untreated RAG1-/- recipients are capable of inducing chronic colitis, the onset and severity of disease is critically dependent upon the composition of intestinal bacteria." (PMID 34358240, 2021). "Chronic colitis was induced in Rag1 KO mice by passive transfer with CD45RBhiCD4+CD25– naïve T cells from C57BL/6J mice exhibiting severe body weight loss, loss of crypts in the colonic mucosa, infiltration of inflammatory cells, and higher levels of IL-17A and IFN-γ production by LPMCs." (PMID 34336843, 2021). "In our study, we observed significantly increased abundance of Tregs in the colon in Foxp3eGFP reporter mice after treatment with rTsPmy (data not shown), and these Tregs were able to significantly inhibit chronic colitis induced by naïve T cells in Rag1 KO mice." (PMID 34336843, 2021). "Multiple studies using the adoptive T-cell transfer model of chronic colitis indicated that the transfer of LFA-1 deficient T cells failed to induce chronic colitis in RAG-1−/− recipient mice, whereas the transfer of wild-type T cells induced severe colitis in the same immunodeficient recipients." (PMID 38787206, 2024). "To determine if T cell intrinsic TLR7 signaling contributes to the development of chronic colitis, we transferred CD4+ CD45RBhi naive T cells isolated from wild-type (WT) or Tlr7-/- mice into Rag1-/- mice and monitored for development of inflammatory disease." (PMID 39464882, 2024). "Note that in this chronic colitis model, transfer of Treg-depleted CD4+CD45RBlo T cells into RAG-1-/- mice was characterized by a Th1<Th17 cytokine signature in the colon tissues, whereas transfer of CD4+CD45RBhi naïve T cells demonstrated a Th1>Th17 cytokine signature." (PMID 34992594, 2021). "For chronic colitis, we used three cycles of DSS exposure in RAG‐1−/− and WT mice." (PMID 32567222, 2020). "The results are consistent with the investigation of H. polygyrus infection-induced Tregs, in which adoptive transfer of Tregs from the cLP of H. polygyrus-infected mice as opposed to uninfected-mice significantly inhibited chronic colitis induced by CD4+CD25– T cells in Rag1 KO mice." (PMID 34336843, 2021).